MCL1 (MCL1 apoptosis regulator, BCL2 family member)
Diseases named in the same sentence as MCL1 in open-access papers (continued):
Sharing a sentence is not in itself a finding about the gene and the disease.
multiple myeloma (continued). "In 2011, a research revealed that the overexpression of miR-29b downregulates myeloid-cell leukemia 1 (Mcl-1), which in consequence triggers the apoptosis of multiple myeloma cells." (PMID 35011442, 2021). "Many cancers, including myeloma, frequently escape apoptosis through the upregulation of anti-apoptotic proteins such as bcl2, bclxl and Mcl1; therefore, pyroptosis induction provides an alternate therapeutic option." (PMID 33066043, 2020). "We determined the sensitivity to BCL2 and MCL1 inhibitors of 60 consecutive myeloma samples (23 at diagnosis and 37 at relapse) with a percentage of plasma cells of at least 3%." (PMID 32371863, 2020). "USP24, which is closely related to USP9X, also plays a critical role in the survival of myeloma B cells by regulating MCL1 protein levels." (PMID 32354135, 2020). "The first MCL1-targeting PROTAC dMCL1-2 contains thalidomide and an MCL1 inhibitor A-1210477, which can successfully degrade MCL1 at nM concentrations in multiple myeloma OPM2 cells." (PMID 32404196, 2020). "MCL1 overexpression has been identified as a vital survival factor in lymphoma, leukemia, and multiple myeloma." (PMID 32404196, 2020). "Overall, these data demonstrate a key role for MCL-1 in myeloma cell survival and for the efficacy of established backbone therapeutics in MM." (PMID 33308268, 2020). "On the other hand, MCL1 BH3-mimetics have demonstrated that a large proportion of myeloma cell lines and patient samples rely on MCL1 for survival." (PMID 32371863, 2020). "The Mcl-1 protein, a Bcl-2 family member, has been demonstrated to be particularly important for the survival of myeloma cells." (PMID 32405334, 2020). "Accordingly, high BCL-2 relative to low MCL-1 expression was reported to indicate BCL-2 inhibitor sensitivity in multiple myeloma, mantle cell lymphoma and Philadelphia-chromosome positive ALL39–41." (PMID 31358732, 2019). "The initiation of autophagy increases several anti-apoptotic factors, such as BCL-2 (B-cell lymphoma 2) and MCL-1 (Myeloid cell leukemia 1), which promotes multiple myeloma (MM) progression." (PMID 31013961, 2019). "S63845 has a high affinity to the BH3-binding groove of MCL1, showed preclinical activity against multiple myeloma, leukemia, and lymphoma cells, and is currently being tested in phase I studies." (PMID 31370269, 2019). "As a consequence, myeloma is primarily dependent on MCL1 and inhibitors of MCL1 have shown promising pre-clinical activity." (PMID 31231360, 2019). "More recently, S63845 a small molecule that binds with high affinity to the BH3-binding groove of MCL1 has been shown to kill MCL1-dependent cancer cells, including multiple myeloma, leukaemia and lymphoma cells." (PMID 30792387, 2019). "AZD5991 is another specific inhibitor of MCL1 that induces apoptosis at low nanomolar concentrations in MCL1-dependent multiple myeloma cell lines." (PMID 31370269, 2019). "Very recently a new MCL-1 inhibitor, S63845, was described and demonstrated both in vitro and in vivo efficacy against MCL-1 dependent myeloma, leukemia, and lymphoma cells." (PMID 30728900, 2019). "This compound induced cell death as a single agent and synergized with ABT-263 to produce apoptosis in multiple myeloma and small lung cancer cell lines that were dependent on MCL-1 for cell survival." (PMID 30720718, 2019). "Transient transfection of miR-27b-3p and miR-214-3p inhibitors demonstrates cooperation between these two miRNAs in the expression of the anti-apoptotic factor MCL1, suggesting that miR-27b-3p and miR-214-3p negatively regulate myeloma fibroblast apoptosis." (PMID 31698726, 2019). "Our studies demonstrate that AZD5991 binds directly to Mcl-1 and induces rapid apoptosis in cancer cells, most notably myeloma and acute myeloid leukemia, by activating the Bak-dependent mitochondrial apoptotic pathway." (PMID 30559424, 2018).
multiple myeloma (continued). "In multiple myeloma (MM) cells, HHT showed anti-myeloma effect with concomitant targeting of the myeloma-promoting molecules, Mcl-1, XIAP, and beta-catenin." (PMID 29788973, 2018). "Here they report a macrocyclic molecule with high selectivity and affinity for Mcl-1 that exhibits potent anti-tumor effects as single agent and in combination with bortezomib or venetoclax in preclinical models of multiple myeloma and acute myeloid leukemia." (PMID 30559424, 2018). "Plasma cells are known to depend on MCL-1 for survival and, following malignant transformation, multiple myeloma cells appear to preserve this dependency." (PMID 30406027, 2018). "The BCL-2/MCL-1 ratio has been proposed as predictor of in vitro sensitivity to navitoclax in human myeloma cell lines." (PMID 29682179, 2018). "In fact, expression of Mcl‐1 and Bcl‐xL was the underlying mechanism driving drug resistance to ABT‐199 in myeloma cells." (PMID 29761903, 2018). "Increased levels of MCL-1 have been observed in multiple myeloma and shown to correlate with disease progression." (PMID 30671383, 2018). "Expression of pro-survival BCL-2 family protein MCL-1 is essential for survival of malignant PC in multiple myeloma (MM)." (PMID 30524962, 2018). "In conclusion, we found that YM155 exerts robust anti-myeloma activity through inhibition of survivin and Mcl-1." (PMID 29340073, 2017). "The IL6/STAT3 activation enhances myeloma cell survival through the activation of anti-apoptotic genes, Mcl-1, Bcl-XL and c-Myc oncogene." (PMID 28458781, 2017). "We conducted experiments to examine the effects of Mcl-1 or survivin overexpression on the cytotoxicity of YM155 in myeloma cells." (PMID 29340073, 2017). "In some cell types, such as chronic myelogenous leukemia and multiple myeloma, the forced reduction of MCL-1 permits BAK oligomerization, activation and is sufficient enough to induce apoptotic cell death." (PMID 28659182, 2017). "The expression of Mcl-1 protein was profoundly suppressed by 6h YM155 treatment in all three myeloma cells in dose- and time-dependent manner." (PMID 29340073, 2017). "Inhibition of Eg5 by filanesib causes an aberrant mitotic arrest and apoptosis in Mcl-1 dependent myeloma cell lines that are able to degrade Mcl-1 during mitotic arrest." (PMID 29163849, 2017). "Compound A-1210477, a derivative of indole-2-carboxylic acids, has been found to selectively and directly bind MCL-1, induce intrinsic apoptosis and demonstrate single agent killing of multiple myeloma and NSCLC cell lines." (PMID 28659182, 2017). "The role of the positive RNA Pol II regulator, P-TEFb (positive transcription elongation factor b), in maintenance of the anti-apoptotic protein Mcl-1 and bortezomib (btz) resistance was investigated in human multiple myeloma (MM) cells." (PMID 28938651, 2017). "In multiple myeloma cells, FTY720-induced ROS activity promotes autophagy, reduces the expression of Mcl-1, Survivin, Bcl-2 and increases cleavage of Bid, ultimately leading to apoptosis of multiple myeloma cells." (PMID 29234668, 2017). "In particular, considering previous studies on the molecular effects of Metformin, alone or in combination with other therapeutic compounds, in solid tumor cell models and in multiple myeloma cells, we have first investigated the expression levels of Mcl-1." (PMID 26959881, 2016). "Recently, the SK2 selective inhibitor, ABC294640 was demonstrated to induce proteasomal degradation of c-Myc and myeloid cell leukemia 1 (Mcl-1) in multiple myeloma cells." (PMID 26934645, 2016). "Knockdown of Mcl-1 in both wild type and PRL-3-overexpressing myeloma cells confirmed that Mcl-1 is an essential survival factor in these cells." (PMID 27036022, 2016).
multiple myeloma (continued). "To study if Mcl-1 was essential for PRL-3-mediated myeloma cell survival we did knockdown experiments of Mcl-1 in INA-6-MOCK and INA-6-PRL-3." (PMID 27036022, 2016). "Proliferating hematopoietic cells, including myeloma cells, are particularly dependent on Mcl-1 and thus particularly sensitive to inhibition of KSP." (PMID 27363832, 2016). "It is shown that inhibition of Mcl-1 results in apoptosis and sensitization to chemotherapeutic drugs in various tumor cells, including multiple myeloma." (PMID 27036022, 2016). "Our results show that Mcl-1 and its transcription factor PU.1 were drastically down-regulated under R-CR8, S-CR8, and MR4 treatment, confirming works on Mcl-1 in other malignancies such as chronic lymphocytic leukemia, neuroblastoma, or multiple myeloma." (PMID 26184865, 2015). "In chronic lymphocytic leukemia, the PIM inhibitor SGI-1776 induces apoptosis by decreasing Mcl1 express via a global block in RNA synthesis, and in multiple myeloma the mechanism of action is by blocking translation and inducing autophagy." (PMID 26472029, 2015). "For instance, high MCL1 expression in multiple myeloma was correlated with recurrence after chemotherapy and shorter survival and mice bearing MCL1 overexpressing lymphomas were less sensitive to cyclophosphamide treatment in vivo." (PMID 25749045, 2015). "A-1210477 induces the hallmarks of intrinsic apoptosis and demonstrates single agent killing of multiple myeloma and non-small cell lung cancer cell lines demonstrated to be MCL-1 dependent by BH3 profiling or siRNA rescue experiments." (PMID 25590800, 2015). "In line with this notion, JNJ-26481585 has previously been described to act by downregulation of Mcl-1 and upregulation of Bid and Bim cells in multiple myeloma cells." (PMID 26473375, 2015). "The anti-apoptotic protein Mcl-1 plays a major role in multiple myeloma (MM) cell survival as well as bortezomib- and microenvironmental forms of drug resistance in this disease." (PMID 24594907, 2014). "Based on these results, we re-evaluated the expression, association with molecular entities and prognostic significance of Mcl-1 in multiple myeloma." (PMID 25296978, 2014). "The apoptotic action of ATO has been shown to involve downregulation of the anti-apoptotic protein Mcl-1 in several cell systems, including myeloma and myeloid leukemia cells and, in many cases, upregulation of the pro-apoptotic proteins Bax and/or Bim." (PMID 24956101, 2014). "Although the Mcl-1 gene has been studied extensively in multiple myeloma and leukemia, there are rare reports on Mcl-1 analysis in head and neck cancer." (PMID 25409302, 2014). "In particular, multiple myeloma cells display high expression of MCL1 and appear to be dependent on MCL1 for survival." (PMID 26556430, 2014). "The findings in this study indicated that RNA silence of STAT3, PI3K, or MAPK gene using shRNA interference robustly inhibited MCL-1 expression in IL-6 treated human MM cells, leading to remarkable myeloma cell apoptosis." (PMID 25422792, 2014). "MCL-1 overexpression has been reported in chronic and acute myeloid leukemias, multiple myelomas, hepatocarcinomas, non-small-cell lung cancers, and sarcomas." (PMID 24260268, 2013). "In myeloma cells, Mcl-1-mediated apoptosis has been reported to be regulated by its interaction with proapoptotic Bim." (PMID 21179037, 2011). "Previous study found that VEGF protects multiple myeloma cells against apoptosis by up-regulating Mcl-1 protein in a time-dependent manner, peaking at 6 h and returning to baseline after 24 h; change in Mcl-1 mRNA expression was not reported." (PMID 20085644, 2010). "Increased Mcl-1 expression has already been demonstrated for other malignancies, e.g. multiple myeloma and non-small cell lung cancer." (PMID 17014711, 2006). "Mcl-1 has been demonstrated to be highly expressed in various human tumor specimens, e.g. in multiple myeloma, non-small cell lung cancer and liver metastasis of colorectal cancer." (PMID 17014711, 2006).
multiple myeloma (continued). "We found that Atiprimod downregulated the levels of Bcl-2, Bcl-XL, and Mcl-1, and induced apoptotic cell death in U266-B1 myeloma cells." (PMID 15970928, 2005). "The activation of STAT3 in myeloma cells results in the upregulation of antiapoptotic proteins of the Bcl-2 family, such as Bcl-2, Bcl-XL, and Mcl-1, thus providing MM cells with a survival advantage." (PMID 15970928, 2005). "Similarly, pyoluteorin-derived analogs such as KS18 have shown remarkable efficacy in xenograft models of drug-resistant multiple myeloma, reinforcing the therapeutic relevance of Mcl-1 inhibition in resistant cancers." (PMID 41149606, 2025). "This may, in part, be due to the identification that PCa models with MCL1 copy number gain, such as 22Rv1 cells, are more sensitive to MCL1 inhibition, which is in keeping with other tumor types including multiple myeloma and lung adenocarcinoma." (PMID 41438049, 2025). "Similarly, combining filanesib with inhibition of the pro-survival factor, MCL-1, enhanced mitotic cell death in multiple myeloma cells, rationalizing studies to further explore this combination." (PMID 40002279, 2025). "In addition, in a phase I study of the MCL1 inhibitor AMG-176 against relapsed or refractory multiple myeloma, treatment-emergent adverse events of grade 3 or higher occurred in 62% of patients, the most common being neutropenia, anemia, and hypertension." (PMID 39122703, 2024). "dMCL1-2 degraded MCL1 at nanomolar concentrations in multiple myeloma (MM) OPM2 wild type cells." (PMID 39372954, 2024). "Additionally, the ratio of MCL-1 to BCL-2 expression determined the response to VEN in myeloma cell lines." (PMID 39052583, 2024). "KS18 efficiently reduces Mcl-1 levels, whereas bortezomib obstructs proteasome function, and dexamethasone alters glucocorticoid receptor signaling, thus enhancing apoptotic stress on myeloma cells." (PMID 39411073, 2024). "Mcl-1, a protein that promotes survival, is involved in the survival of myeloma cells." (PMID 37046991, 2023). "However, multiple myeloma cells are frequently more dependent on MCL-1 for survival, conferring resistance to venetoclax." (PMID 37956312, 2023). "In myeloma, the sensitivity of cells to venetoclax is strongly associated with the t translocation, since it more likely presents with high BCL2 expression and low MCL1 or BCL-XL expression." (PMID 35799216, 2022). "In multiple myeloma, MCL-1 strongly binds to BIM, thereby blocking apoptosis." (PMID 35563853, 2022). "Furthermore, inactivation of MCL‐1 by filanesib can sensitize multiple myeloma cells to dexamethasone." (PMID 34921527, 2022). "In addition, high MCL1/BCL2 or BCL-XL/BCL2 mRNA ratio indicates that myeloma cells resist venetoclax." (PMID 35799216, 2022). "The ratio of BCL2, BCL-XL and MCL1 expression in myeloma cell lines, primary cells and patient samples in clinical trials has been associated with venetoclax sensitivity, suggesting variable relative dependencies on these pro-survival proteins as a driver of intrinsic resistance." (PMID 35659041, 2022). "Indeed, MCL1 inhibition is currently in early clinical testing for multiple myeloma and MYC positive diffuse large B-cell lymphoma (DLBCL) with promising results (Clinicaltrails.gov, NCT02992483)." (PMID 34654952, 2022). "The ability of a new Gal-3 antagonist, GCS-100, to induce myeloma cell death by modulating MCL1 apoptosis regulator BCL2 family member (MCL-1), phorbol-12-myristate-13-acetate-induced protein 1 (NOXA), and the cell cycle was assessed in the U266 and RPMI 8226 cell lines." (PMID 36364232, 2022). "Additionally, the combination of glucocorticoids with inhibitors of Bcl-2 or MCL-1 such as venetoclax and bortezomib, respectively, has been shown to be a promising and safe treatment for relapsed/refractory multiple myeloma." (PMID 36539401, 2022).
multiple myeloma (continued). "Myeloid cell leukemia 1 (Mcl-1) is an antiapoptotic Bcl-2 family member and is one of the most frequently overexpressed proteins in human cancers, including lung cancer, colorectal, liver, prostate cancer, and multiple myeloma." (PMID 35301297, 2022). "In results from in vitro chemosensitivity as well as BH3 profiling assays, which have both been previously shown to predict patient responses to BH3 mimetics, we consistently found that clonal plasma cells in AL amyloidosis can be highly dependent on MCL-1, or BCL-2 for survival, or both." (PMID 36184661, 2022). "Based on our results, highly primed clonal plasma cells from patients with AL amyloidosis would be sensitive to single agent treatment with a proteasome inhibitor, dexamethasone, or an inhibitor of MCL-1 or BCL-2, especially, when treatments are assigned with biomarkers such as BH3 profiling." (PMID 36184661, 2022). "Mcl-1 is an antiapoptotic protein known to play an essential role in myeloma cell survival." (PMID 35127532, 2021). "Thus, inhibition of Mcl-1 offers an attractive target and a promising strategy for myeloma treatment." (PMID 34349655, 2021). "Notably, as also reported in multiple myeloma and CLL, VEN sensitivity is strongly and inversely correlated with the BCL-2/MCL-1 ratio, with a loss of AML cell sensitivity when high levels of MCL-1 are expressed." (PMID 35008186, 2021). "Other haematological malignancies expressing high levels of both Bcl-2 and Mcl-1, such as multiple myeloma, may also benefit from the venetoclax and ATO combination, which needs to be validated in future research." (PMID 33858507, 2021). "Dexamethasone, for example, is leading to Bcl-2 dependence and sensitization to venetoclax in multiple myeloma by altering the balance between pro- and antiapoptotic Bcl-2 protein members (increased Bim and decreased Mcl-1 vs. Bcl-2 upregulation), making Bcl-2 expression essential for survival." (PMID 34063867, 2021). "Besides, the distribution of BIM among BCL-2 proteins was described to favor BCL-2/BCL-xL co-dependencies in MCL-1 dependent myeloma cells." (PMID 34781947, 2021). "However, a clinical phase I dose-escalation study for treatment of multiple myeloma, non-Hodgkin lymphoma, or acute myeloid leukemia by the Mcl-1 inhibitor AMG 397 was terminated due to cardiac toxicity." (PMID 34028599, 2021). "Moreover, in clinical trials of venetoclax, the ratios of Bcl-2/Mcl-1 and Bcl-2/Bcl-xL transcripts correlated to a greater degree than the level of Bcl-2 mRNA alone with efficiency of venetoclax in multiple myeloma patients." (PMID 35008345, 2021). "Thus, inhibition of the Mcl-1 protein considered as a therapeutic strategy to kill the myeloma cells." (PMID 34349655, 2021). "As a protein highly expressed in a number of B-cell lymphomas, Bcl-2 is expressed in Chronic lymphocytic leukaemia (CLL), Mantle cell lymphoma (MCL), Multiple myeloma (t11;14) (MM) or solid tumors, and (in a similar manner to Mcl1 expression) is critical for cell survival." (PMID 34753495, 2021). "Besides, depsipeptide, as an HDACI, decreases the expression of Bcl-2, Bcl-XL, and Mcl-1 in multiple myeloma cells." (PMID 34903991, 2021). "H19 over-expression increases resistance to bortezomib by targeting miR-29b-39 to increase myeloid cell leukemia 1 (MCL-1) expression in multiple myeloma cells and to cisplatin by targeting miR-106b-5p to enhance testis development-related 1 (TDRG1) expression in seminoma cells." (PMID 32272875, 2020). "Finally, MCL-1 plays not only a role in myeloma survival and drug resistance but also in the efficacy of established drugs." (PMID 33308268, 2020). "In addition, we found that S63845/venetoclax combination exhibited marked anti-tumor activity in the U266 xenograft model resistant to both inhibitors, in agreement with studies that report efficacy of venetoclax with MCL1 inhibitors in myeloma models." (PMID 32371863, 2020).